RN7SL724P (RNA, 7SL, cytoplasmic 724, pseudogene)
Gene: Miscellaneous RNA gene on chromosome 3 (139,609,669 to 139,609,939, reverse strand). Ensembl gene ENSG00000244692.
Homologues: Orthologues: chimpanzee Metazoa_SRP (98% identical), macaque Metazoa_SRP (93% identical). Paralogues in human: RN7SL1 (87% identical), RN7SL2 (87% identical), RN7SL3 (86% identical), RN7SL464P (85% identical), RN7SL45P (85% identical), RN7SL126P (84% identical), RN7SL566P (84% identical), RN7SL709P (84% identical), RN7SL678P (83% identical), RN7SL186P (83% identical), RN7SL220P (83% identical), RN7SL479P (83% identical), and 708 more.